LCN2 (lipocalin 2)
Diseases named in the same sentence as LCN2 in open-access papers (continued):
Sharing a sentence is not in itself a finding about the gene and the disease.
infection (continued). "Lipocalin-2 (LCN2), also known as neutrophil gelatinase-associated lipocalin, is an acute-phase protein that protects the body against infection by sequestering iron." (PMID 34829528, 2021). "This depletion protected Lcn2-/- mice from exaggerated weight loss between day 4 and 7 post infection, indicating that CD8+ T cells mediate the increased weight loss during this time period." (PMID 33905460, 2021). "Lipocalin-2 (also known as neutrophil gelatinase-associated lipocalin or siderocalin) is expressed in human neutrophils in response to infection/inflammation and ischemia and is involved in innate immunity and apoptosis." (PMID 33382822, 2020). "In this study, we showed that upon infection with Escherichia coli (O157:H7), Lcn2-deficient (Lcn2−/−) mice carried more bacteria in blood and liver, and the acute-phase sera lost their antibacterial activity in vitro." (PMID 31781104, 2019). "For example, host lipocalin-2 was shown to reduce the growth of pathogenic E. coli H9049 by binding bacterial siderophores and reducing the availability of iron during infection of mice." (PMID 30984629, 2019). "Lipocalin-2 knock-out mice (Lcn2−/− mice) are more susceptible to infection by siderophore-producing pathogens, such as Klebsiella pneumonia and Escherichia coli." (PMID 30534124, 2018). "Vertebrates also produce lipocalin-2, or neutrophil gelatinase-associated lipocalin (NGAL), which is secreted by neutrophils in response to infection, and captures bacterial siderophores." (PMID 27982111, 2016). "The genes used (matrix metallopeptidase 9, olfactomedin 4, NB1 glycoprotein and lipocalin 2) were previously identified as predictive for severity of disease caused by infection with respiratory syncytial virus (RSV)." (PMID 26298058, 2015). "LCN-2 also known as neutrophil gelatinase associated lipocalin is a component of the innate immune system with a key role in the acute-phase response to infection." (PMID 24106481, 2013). "Transformation of E. coli with the iroA locus is sufficient to cause lethal infection in Lcn2+/+ mice." (PMID 19834550, 2009). "Conversely, co-injection of E. coli and a siderophore to which Lcn2 cannot bind causes lethal infection in Lcn2+/+ mice." (PMID 19834550, 2009). "While urinary iron levels increase slightly during infection, Fe bioavailability may be limited by neutrophil gelatinase-associated lipocalin (NGAL), also called lipocalin-2 (Lcn2) or siderocalin (Scn) Lcn2 can bind to both apo- and ferric enterobactin." (PMID 40569986, 2025). "LCN2, a neutrophil-associated protein, exerts antimicrobial effects through its ability to sequester bacterial siderophores, thereby inducing iron deprivation and representing a novel mechanism of host defense against infection." (PMID 41196851, 2025). "Upon infection, Villin-Lyz1TG mice demonstrated a significantly increased morbidity reflected by severe body weight loss, increased mortality, and elevated cecum lipocalin 2 (LCN2) (p = 0.0013), an indicator of inflammation." (PMID 38823640, 2024). "The expression levels of Lcn2, which encodes for the antimicrobial protein lipocalin-2, and of S100a8 and S100a9, whose gene products together form the antimicrobial protein calprotectin, were increased during infection but were comparable between WT mice and Il22−/− mice." (PMID 38557196, 2024). "During infection, the body uses some iron-binding proteins to control the iron supply accessible to microbes, such as neutrophil gelatinase–associated lipocalin (NGAL or lipocalin-2), lactoferrin, and natural resistance–associated macrophage protein 1 (NRAMP1)." (PMID 37629516, 2023). "In the present experimental and clinical study, by employing proteomic analysis in both neonatal mice and preterm infants, we identified LCN2 as a promising marker for preterm infection/inflammation associated with cerebrovascular alterations and neuroinflammation." (PMID 37496672, 2023).
infection (continued). "Thus, the results in preterm infants experiencing infection/inflammation, showing associations with LCN2 and vascular changes, are in line with our results in neonatal S. epidermidis infected mice." (PMID 37496672, 2023). "This experimental and clinical study suggests that LCN2 may be a marker of preterm infection/inflammation associated with cerebrovascular changes and neuroinflammation." (PMID 37496672, 2023). "This difference may be caused by time point of clinical infection patients, and patients come to the hospital only when the apparent symptoms appear, as neutrophils are generated enriched at early infection and LCN2 is mainly expressed in neutrophils." (PMID 35495713, 2022). "Together these findings suggest that nutritional immunity, and specifically LCN2, play critical roles in the innate immune response to A. baumannii and that the influence of this neutrophil-associated protein on the outcome of infection is likely multifactorial." (PMID 36054235, 2022). "Consistent with the observation that the Lcn2-deficient mice exhibited more severe symptoms of infection when employing the lower infectious dose, we found that 60 percent of these mice met humane endpoint criteria by 30 h, whilst none of the WT mice required euthanasia at this timepoint." (PMID 36054235, 2022). "Lipocalin‐2 (LCN2), also known as 24p3 or neutrophil gelatinase‐associated lipocalin (NGAL), is a 25‐kDa protein that is acutely produced and secreted from neutrophils, astrocytes, endothelial cells, and microglia in response to infection, inflammation, and injury." (PMID 33421207, 2021). "The differences in CSF LCN2 levels between laboratory-confirmed and clinically suspected BM groups pointed to the association between the host responses and an ongoing infection (i.e. the presence of a bacterial pathogen in clinical samples at the time of collection)." (PMID 32659386, 2020). "Interestingly, it has been suggested that lipocalin-2 selectively restricts the growth of pathogenic E. coli and provides an advantage to commensal E. coli during infection by the pathogen." (PMID 30984629, 2019). "Protein levels of Lipocalin-2 (LCN-2), a molecule implicated in antimicrobial defense and innate immunity, were also increased in cecal tissue homogenates in B6+/- mice compared to B6-/- mice after infection." (PMID 26133982, 2015). "In addition, in response to acute intratracheal high dose infection with virulent M.tuberculosis H37Rv, mice deficient in Lcn2 are more susceptible than wild type (WT) infected mice." (PMID 23185529, 2012). "Accordingly, Lcn2-deficient mice (Lcn2−/−) succumb to infection." (PMID 19834550, 2009). "Additionally, it was shown that during acute anemia, the expression of NGAL is reduced in erythroid cells by a feedback system We conclude that patients with low Lcn2 levels (e.g., during acute anemia) are at high risk of infection even if E. coli strains carry only one siderophore." (PMID 40569986, 2025). "Furthermore, LCN2-deficient mice are highly susceptible to intratracheal infection with Mtb." (PMID 37822359, 2023). "Although, the primary aim of the current study was to identify molecular changes associated with infection/inflammation in both mice and human, the concomitant increase in LCN2, CRP and IL6, that we found in this study, might aid in recognizing preterm infants experiencing infection." (PMID 37496672, 2023). "Compared to control infections with the original wild-type S. Typhimurium strain, the evolved population reached equivalent gut-luminal densities (≈109Salmonella cells per gram feces), but caused significantly less gut inflammation, as judged by a reduced lipocalin-2 concentration in the feces." (PMID 37651408, 2023).
infection (continued). "Lcn2 and its encoded protein are strongly upregulated in mammals in response to exposure to purified LPS, Gram-negative bacteria, mycobacteria, and various parasites, and the effects of LCN2 deficiency appear to be pleiotropic and dependent upon the pathogen and route of infection." (PMID 36054235, 2022). "Lipocalin-2 (LCN2) is expressed in pathological conditions such as intoxication, infection, inflammation, and other forms of cellular stress." (PMID 40563995, 2025). "Lcn2 production is a host response to inflammation and infection and it is often used as a fecal marker for intestinal inflammation." (PMID 41381568, 2025). "ELISA results revealed a significant increase in Lcn2 protein level in lung homogenates after infection with P7 compared to the P0 group at 3 and 5 dpi (P < 0.001)." (PMID 39180285, 2025). "The concentration of fecal lipocalin-2, a marker of intestinal inflammation, was significantly elevated in mice starting 3 d after infection with the S. Typhimurium wild type compared to mice infected with an avirulent S. Typhimurium invA spiB mutant." (PMID 40938708, 2025). "The concentrations were increasing up to 13 days postinfection (from ∼3 to 27 ng/ml), correlating with CDT-induced changes in mucin thickness, decreased number of goblet cells, and increased fecal lipocalin-2 levels sustained throughout the infection." (PMID 41443420, 2025). "NGAL, also known as lipocalin-2, is an acute-phase protein induced by injury, infection, or other inflammatory stimuli, recently identified as a new inflammatory constituent of the pathophysiology of AD." (PMID 39850411, 2025). "Lipocalin-2 (LCN2) - also known as neutrophil gelatinase-associated lipocalin, siderocalin or 24p3 - is an acute-phase glycoprotein rapidly upregulated during infection and sterile inflammation." (PMID 41019093, 2025). "LCN2, also known as neutrophil gelatinase-associated lipocalin (NGAL), serves as a key inflammatory marker closely linked to infection and inflammation." (PMID 41306613, 2025). "Lipocalin 2 (LCN2), also known as neutrophil gelatinase-associated lipocalin (NGAL), has been studied in various conditions, such as inflammation, infection, and metabolic diseases." (PMID 41227378, 2025). "In normal physiology, LCN2 is an innate immune protein secreted by neutrophils and macrophages in response to inflammation and infection." (PMID 41303420, 2025). "NGAL, also known as lipocalin-2, is an adipokine involved in metabolic homeostasis, apoptosis, infection, immune response, and inflammation." (PMID 41402737, 2025). "To determine the source of Lcn2 in the lung following P7 infection, we conducted immunofluorescence staining." (PMID 39180285, 2025). "Infection elicits an inflammatory response and dysregulates genes associated with the innate immune system (CCL20, CD38, LCN2 and NR4A3)." (PMID 39666439, 2025). "The Chao1, Shannon, Simpson, and observed species indices revealed notable differences between wild-type and Lcn2 knockout mice during the 1- to 5-week period following infection with the M. tuberculosis complex." (PMID 39051782, 2024). "In murine cauda epididymis, Lcn2 mRNA was significantly increased after infection with uropathogenic E. coli, highlighting the antibacterial activity of LCN2 in reproductive tissues as seen in female uterine tissue." (PMID 38645429, 2024). "Infection with Spn significantly increased expression of Cxcl1, Cxcl2 and lipocalin-2 (Lcn2), a marker of inflammation, in infant mice compared to adults." (PMID 38718049, 2024). "Lcn-2 is a multifunctional protein involved in inflammation regulation, infection defense, iron homeostasis, and cell migration and differentiation, among other physiological processes." (PMID 38533497, 2024). "In both infection scenarios, S100a8-supplemented MN mice showed less intestinal and also less systemic inflammation as measured by restricted increases of Lcn-2 levels in the stool and blood upon infection compared to untreated MN pups." (PMID 39366940, 2024).
infection (continued). "Subsequently, Lcn-2 was isolated from human neutrophil granules and mouse kidney cells released during infection and inflammation." (PMID 38533497, 2024). "This is interesting because LCN2 plays a role in innate immunity and serves as a host defense mechanism against infection by sequestering iron-containing compounds called siderophores, which are essential for bacterial growth." (PMID 38101300, 2024). "Consistent with infection titres, Lcn2 treatment resulted in marked increases in soft tissue accumulation surrounding the infected implanted catheter." (PMID 38567642, 2024). "During the acute phase of infection, blood levels of hepcidin and LCN2 increased rapidly, whereas iron levels decreased, with values in 95.8% of cases below the normal range (40–188 μg/dL)." (PMID 37932342, 2023). "During infection and inflammation four AMPs are expressed in MSCs, i.e., cathelicidin LL-37, human β-defensin-2 (hBD-2), hepcidin and lipocalin-2 (Lcn2)." (PMID 36675259, 2023). "To this end, the CONX mice were shifted to high-fat diet for 24 h before infection with a 100:1 mixture of wild-type S. Typhimurium versus S.TmhilD and we analyzed gut luminal growth of the Salmonella strains and fecal lipocalin-2 concentrations for 40 days." (PMID 37651408, 2023). "For instance, lipocalin-2 decreased the growth of E. coli H9049 by reducing the availability of iron during infection of mice." (PMID 37990046, 2023). "LCN2 is secreted from various cells and can be detected in blood plasma and urine, making it an important biomarker of inflammation, infection, and organ damage." (PMID 37779143, 2023). "We found that ‘LCN2(NGAL),’ ‘MHCII expression by monocytes,’ ‘IL-6,’ and ‘Anticoagulant treatment’ revealed distinct patterns associated with severe infection outcomes." (PMID 37598150, 2023). "These two cell types, typically defined by expression of Ly6g (neutrophils) and Adgre1 (F4/80, macrophages), expressed a similar transcriptional program following infection, including S100a8/9, Lcn2, Cxcl1, and Il1b." (PMID 38096412, 2023). "To further delineate the involvement of LCN2 in hippocampal vessel alterations following infection, we performed a network analysis including the regulatory molecules previously identified by IPA." (PMID 37496672, 2023). "In the severe infection group, a machine learning model identified LCN2/NGAL, IL-6, and monocyte activation as parameters associated with fatality while anti-coagulant therapy was associated with survival." (PMID 37598150, 2023). "In the recovery phase (D10), as the immune system and treatment brought the infection under control, WBC and levels of IL-6, CRP, hepcidin, and LCN2 substantially decreased compared to the acute phase of infection." (PMID 37932342, 2023). "Both neutrophils and macrophages showed upregulation of some genes related to pathogen resistance/interferon response/infection in ALF mice (Lcn2, Ifi209, and Saa3), indicating that ALF leads to activation of myeloid cells in the intestine." (PMID 37488127, 2023). "It is becoming clearer how LCN2 acts in the innate immune system’s protection against pathogens and infections." (PMID 37240031, 2023). "The results highlight that LCN2 has the potential to become a complementary biomarker to aid the early diagnosis of infection in preterm infants." (PMID 37496672, 2023). "In our Stz-induced diabetic model we confirmed that CP and LCN2 abundances were increased during infection in wound tissue from Db mice compared to nDb mice." (PMID 37358277, 2023). "Fourth, we only investigated alveolar macrophages, although LCN2 also plays roles in neutrophils, another important innate immune cell subset that protects against infection." (PMID 36923935, 2023). "Of note, at this time point of infection, in both GsdmD+/− and GsdmD−/− littermates, we measured high levels of the inflammatory marker lipocalin-2 (LCN2) in the feces." (PMID 37988464, 2023).
infection (continued). "Lcn2 is present at high levels in the urinary tract during infection (40, –, 42); therefore, these in vitro competitions with the addition of Lcn2 are likely a closer representation of UTI." (PMID 35546538, 2022). "The infection rate in the 25 μg/mL LCN2-pretreated group was even lower than that in the general UPEC-infected group." (PMID 36555403, 2022). "can modify the siderophore enterobactin, which can be neutralized by Lcn2, to form salmochelin, a stealth siderophore that cannot be bound by Lcn2, thereby enhancing their survival when the acute phase response of infection and inflammation has been triggered." (PMID 35785195, 2022). "With the finding that LCN2 plays a critical role in infection, this raises the possibility of utilizing LCN2 as a potential therapeutic." (PMID 36054235, 2022). "During infection, very high staining of LCN2 was detected in the livers, which localized with hepatocytes throughout the lobule." (PMID 36054235, 2022). "Restoration of LCN2 via transfection or infection, as well as addition of rhLCN2 in LCN2-KO#1 cells, showed the presumed upregulation of IL-1β." (PMID 35053376, 2022). "Low level LCN2 immunolabeling was detected overall in the spleens, where infection with A. baumannii lead to moderate expression, which localized with red pulp myeloid cells." (PMID 36054235, 2022). "LCN2 not only plays a vital role in antibacterial infection but also functions as a crucial player in the immune response to pathogenic inflammatory stimuli." (PMID 36387401, 2022). "During infection, Ent is captured by the host protein Lcn2, which limits Ent-mediated iron acquisition and hinders bacterial growth." (PMID 36094114, 2022). "Differences between competitive indexes were significant at day 2 and 3 post-infection (p.i.), correlating with the onset of inflammation quantified by measuring the amount of Lipocalin 2 (LCN2) in the feces." (PMID 35389980, 2022). "Given the apparent induction of the hypoferremia of infection/inflammation by A. baumannii within the host, further highlighting the importance of iron during infection, we next sought to elucidate if LCN2 can inhibit acquisition of this metal by A. baumannii." (PMID 36054235, 2022). "An important caveat to our study, however, is highlighted by the observation that different bacterial inocula can impact the outcome of infection, as exemplified by increased disease severity in the Lcn2-/- mice when a higher inoculum was used." (PMID 36054235, 2022). "After LCN2 pretreatment for 24 h, the UPEC-infection-induced secretion of both extracellular IL-8 and IL-6 significantly were reduced in all LCN2-treated groups (p < 0.0001 compared to the 15 mM glucose treatment)." (PMID 36555403, 2022). "LCN2, a member of neutrophil granule markers, is stored in the specific granules and can be carried to the local infection area." (PMID 35990970, 2022). "Consistent with the transcriptomics results, infection of WT mice with A. baumannii resulted in broad, multiorgan and multicellular increases in LCN2 immunolabeling, with distinct patterns of localization." (PMID 36054235, 2022). "The CBA analysis of supernatants from cell cultures pretreated with different doses of LCN2 showed inhibitory effects on UPEC-infection-stimulated inflammation." (PMID 36555403, 2022). "Although the role of LCN2 in infection is likely multifactorial, we find its antimicrobial effects are at least partly exerted by impairing iron acquisition by A. baumannii." (PMID 36054235, 2022). "Infection also resulted in reduced LCN2 induction in DMT1fl/flLysMCre(+) macrophages, which was accompanied by an increased intracellular LIP and higher intracellular bacterial burden." (PMID 35743233, 2022). "Consistently, the fecal level of lipocalin-2, an inflammatory marker, was comparable in both groups 9 days post-infection." (PMID 34072947, 2021).